SOST (sclerostin)
Diseases named in the same sentence as SOST in open-access papers (continued):
Sharing a sentence is not in itself a finding about the gene and the disease.
osteoporosis (continued). "In terms of weaknesses, though postmenopausal women are the main target group for osteoporosis treatments such as romososumab, we were only able to examine predicted effects of sclerostin lowering in males and females combined, due to the lack of availability of sex‐specific sclerostin GWAS dataset." (PMID 37096546, 2023). "In this study, serum PINP and osteocalcin were decreased and sclerostin was increased in SCI rats, and the change of these factors was effectively reverted, which suggests that CIHH enhances osteogenesis and reduces bone resorption, resulting in the improvement of osteoporosis." (PMID 37229453, 2023). "However, the effects of sclerostin inhibition on bone quality in human patients suffering from disuse osteoporosis conditions have not yet been examined in detail." (PMID 33738515, 2022). "To identify a possible role of sclerostin and irisin in osteoporosis and sarcopenia of men, we evaluated the serum sclerostin and irisin levels in rats with orchiectomy (ORX) or sham operation, and analyzed the correlations of the serum sclerostin, irisin levels and BMD and grip strength in rats." (PMID 36456918, 2022). "Evidence revealed that sclerostin was higher as the BMD lower in DM patients, and studies revealed that as renal function worsened, higher levels of sclerostin were present, which highlighted its role in the pathogenesis and high prevalence of osteoporosis in CKD patients." (PMID 35334561, 2022). "Additionally, estrogen was described to have a suppressive effect on the Wnt-signaling antagonist sclerostin, which is lacking in osteoporosis and leads to the suppression of Wnt signaling by active sclerostin." (PMID 35163315, 2022). "However, postmenopausal women without osteoporosis showed no acute sclerostin response to plyometric exercise but have higher levels of resting sclerostin compared to young adult women." (PMID 36685192, 2022). "Based on the positive association between sclerostin levels and BMD, they concluded that sclerostin might be used as a predictor of osteoporosis but should not replace the DEXA for diagnosing osteoporosis." (PMID 35705746, 2022). "Therefore, the results of this study were in accordance with previous studies showing that there was a negative association between sclerostin and BMD and echoed the studies using agents antagonizing the effects of sclerostin to increased BMD and to prevent osteoporosis in post-menopausal women." (PMID 35334561, 2022). "Therefore, sclerostin and DKK-1 neutralizing antibodies (romosozumab and BHQ880) are appealing new strategies for the treatment of inhibition of decreasing bone mineral density and osteoporosis." (PMID 36506070, 2022). "To date, studies using sclerostin antibodies in disuse osteoporosis have not been conducted." (PMID 33435159, 2021). "The literature reports that SOST may be a potential marker for osteoporosis screening but not for fracture prediction." (PMID 32155909, 2020). "As the knowledge about structure and function of sclerostin is progressively unveiled, sclerostin is being suggested as a “predictor” and “biomarker” for diseases such as chronic kidney disease (CKD), aortic valve calcification, osteoporotic fracture or spinal cord injury induced osteoporosis." (PMID 26749312, 2016). "Sclerostin and DKK1 have been shown to be differentially regulated by treatment agents used in osteoporosis with increases in sclerostin and either no change or decreases in DKK1 seen with antiresorptive agents such as bisphosphonates and denosumab, respectively." (PMID 25548714, 2014). "This demonstrates that sclerostin alone may not be a sufficient marker of osteoporosis." (PMID 41594249, 2026). "Accordingly, inhibitors of this pathway, such as sclerostin, Dickkopf-1 (DKK1), WNT inhibitory factor 1 (WIF1), and secreted frizzled-related proteins (SFRPs), have a negative regulatory role in bone formation and may serve as effective therapeutic targets for osteoporosis." (PMID 39606935, 2025).
osteoporosis (continued). "Based on these findings, dual inhibition of sclerostin and DKK1 by administration of a bispecific antibody increased bone formation and improved fracture healing in rodents, suggesting that a simultaneous inhibition of sclerostin and DKK1 may result in superior results in osteoporosis treatment." (PMID 35160258, 2022). "Our study investigated in detail the changes of sclerostin and irisin in ORX process of male rats and their relationship with properties of bone and muscle, indicating for the first time that they might be important endocrine factors involved in sarcopenia and osteoporosis in men." (PMID 36456918, 2022). "Thus, new targets are being studied for the treatment of osteoporosis, such as cathepsin K inhibitors or anti-sclerostin therapies; however, an ideal osteoporosis therapy has not yet been developed, as they still present considerable adverse effects that limit their long-term use." (PMID 36012730, 2022). "Three humanized neutralizing antibodies to sclerostin, a glycoprotein secreted by osteocytes with a negative effect on the formation of bone tissue, are currently in clinical trials, under development, with preclinical and clinical evidence supporting their use in osteoporosis." (PMID 31281368, 2019). "However, though sclerostin levels may initially increase after SCI in response to mechanical unloading, in the long-term, circulating sclerostin may serve as a biomarker of osteoporosis severity and not a mediator of ongoing bone loss." (PMID 25419534, 2013). "Sclerostin concentrations were not correlated to BMD values, adjusted for age, sex and BMI, or presence of osteoporosis (data not shown)." (PMID 34448099, 2022). "Periostin KO mice (Postn-KO) exhibited osteoporosis, and in these mice, mechanical loading and PTH administration did not suppress sclerostin expression or increase cortical bone mass." (PMID 31698687, 2019). "No statistical significance was found between genotypes of SOST rs1234612 and VKORC1 rs9934438 with BMD in postmenopausal Romanian women with osteoporosis." (PMID 31774873, 2019). "Furthermore, we did not use a well-established treatment of osteoporosis such as bisphosphonates, RANK ligand inhibitors, sclerostin inhibitor, and parathyroid hormone in this study." (PMID 40283112, 2025).
sclerosteosis (129 papers, 2007 to 2025). "Loss-of-function mutations that reduce SOST (the gene encoding sclerostin) expression in humans lead to excessive bone formation, as observed in the high bone mass disorder known as sclerosteosis." (PMID 40723914, 2025). "In this study, we report a sclerosteosis 1 proband with a novel homozygous variant which results in loss function of SOST." (PMID 40605263, 2025). "In the present study, we report a sclerosteosis 1 proband with a novel homozygous variant that results in LOF in the Sclerostin locus." (PMID 40605263, 2025). "Pathogenic variants in the SOST gene result in sclerosteosis, van Buchem disease (VBD), or craniodiaphyseal dysplasia." (PMID 40605263, 2025). "SOST‐related genetic disorders are very rare, and limited studies have reported variants associated with sclerosteosis." (PMID 40605263, 2025). "The journey began in 2001 with the discovery of loss-of-function mutations in the SOST gene, encoding for sclerostin, as a cause for the rare high bone mass disorders called sclerosteosis and Van Buchem disease." (PMID 39953279, 2025). "Sclerostin was first described in two rare genetic diseases characterized by loss-of-function mutations in SOST gene: sclerosteosis and Van Buchem disease." (PMID 38634076, 2024). "Further, mutation of SOST in sclerosteosis patients is associated with greater bone mass and body stature." (PMID 38706880, 2024). "A rare human autosomal recessive disease called sclerosteosis, which is characterized by increased bone mass and cortical thickening, is caused by mutations in the sclerostin (SOST) gene." (PMID 38731934, 2024). "Mutations in the SOST gene, leading to a deficiency of SOST, can give rise to two uncommon autosomal recessive bone-hardening conditions: Sclerosteosis and van Buchem disease." (PMID 38711986, 2024). "The discovery that sclerostin deficiency underlies the rare bone disorder sclerosteosis was the first indication that this protein plays a key role in regulating bone mass." (PMID 37490188, 2023). "It was reported that different types of mutations in the SOST gene are responsible for Van Buchem disease and sclerosteosis, both of which are characterized by a considerable increase in bone mass." (PMID 36982995, 2023). "On the contrary, sclerostin depletion can cause diseases including sclerosteosis as well as Van Buchem’s disease." (PMID 37229453, 2023). "Patients with sclerosteosis or Van Buchem disease have a phenotype of increased cementum, and SOST gene deficiency in mice also induces buccal and lingual cementum thickening, which reflects the inhibitory effect of sclerostin on cementogenesis." (PMID 35562828, 2022). "SOST was identified as the causative gene for sclerosteosis 1 (MIM #269500) and van Buchem disease (MIM #239100), which are characterized by a high bone mass, indicating that osteocytes regulate bone mass by producing sclerostin." (PMID 36246908, 2022). "This identified a novel deletion homozygous mutation in the SOST gene (c.387delG, p.Asp131ThrfsTer116) which disrupts sclerostin function, causing sclerosteosis." (PMID 35208525, 2022). "Sclerosteosis is caused by the mutation of SOST gene, whereas Van Buchem disease results from the deletion of a 52-kb fragment containing an enhancer element downstream of the SOST transcription start site." (PMID 35562828, 2022). "Sclerostin was first described as a protein produced by the SOST gene and its deficiency results in sclerosteosis, a disorder characterized by extreme bone overgrowth." (PMID 36145151, 2022). "Mutations in the SOST gene (encoding sclerostin) can cause sclerosteosis; van Buchem disease (VBD) results from osteoblast hyperactivity." (PMID 36124027, 2022). "The osteocyte-secreted protein sclerostin was originally discovered through the identification of loss-of-function mutations in the SOST gene in individuals with the genetic high-bone-mass disorder sclerosteosis (van Buchem disease)." (PMID 33738515, 2022).
sclerosteosis (continued). "Our aim is to describe the clinical and radiological features and the new underlying SOST mutation in a patient with sclerosteosis." (PMID 35208525, 2022). "In humans, SOST mutations are associated with conditions characterized by excess bone formation: sclerosteosis, van Buchem disease, craniodiaphyseal dysplasia and the HBM phenotype." (PMID 35052478, 2022). "Loss of function mutations of the SOST gene—a gene coding for sclerostin—are linked to sclerosteosis." (PMID 35208525, 2022). "Here, we report a novel SOST gene mutation as the cause of sclerosteosis in a patient of Mediterranean origin (Syria) who is living in Saudi Arabia." (PMID 35208525, 2022). "A sclerostin deficiency causes sclerosteosis, which is characterized by an excess bone mass with enhanced bone formation in humans and mice." (PMID 35563281, 2022). "Studies revealed that the loss of sclerostin expression resulted in a high bone mass and increased bone strength in patients with sclerosteosis and Van Buchem disease as well as in sclerostin-deficient mice." (PMID 36456918, 2022). "It is well-known that loss-of-functions mutation in sclerostin (expressed by the SOST gene) cause sclerosteosis." (PMID 34589484, 2021). "Mutations in the sclerostin coding gene cause sclerosteosis with low SOST levels and increased bone formation." (PMID 34698098, 2021). "The function of sclerostin in bone metabolism is illustrated by two rare high bone mass disorders, Sclerosteosis and Van Buchem disease, characterised by deficiency or impaired sclerostin production." (PMID 34290287, 2021). "Sclerostin is a 190-amino-acid secreted glycoprotein that is encoded by SOST, a gene identified in sclerosteosis and van Buchem’s disease patients." (PMID 34830568, 2021). "Sclerosteosis is a high bone mass disorder, caused by pathogenic variants in the genes encoding sclerostin or LRP4." (PMID 35052419, 2021). "The identification of homozygous loss-of-function variants in SOST, which encodes sclerostin, as the genetic cause for sclerosteosis was an important breakthrough in the bone field." (PMID 35052419, 2021). "This was evidenced by the identification of disease-causing variants in LRP4 or SOST in sclerosteosis patients, a severe sclerosing bone disorder specifically characterized by progressive bone overgrowth." (PMID 35052419, 2021). "As the patient was thought to suffer from sclerosteosis, SOST and LRP4 were analyzed for putative variants." (PMID 35052419, 2021). "Sclerosteosis results from a loss-of-function mutation in the sclerostin gene, and Van Buchem disease is caused by deletion of a large regulatory element of the gene." (PMID 34290287, 2021). "Sclerostin was originally discovered because of inactivating mutations in the coding and enhancer regions of the SOST gene that cause the rare high bone mass disorders sclerosteosis and van Buchem disease." (PMID 33776907, 2021). "Sclerostin was first recognized in patients with sclerosteosis, in which inactivating mutations of the sclerostin gene SOST were found to be associated with high bone mass." (PMID 34361085, 2021). "So far, all previously reported sclerosteosis-causing variants are located in the highly conserved cavity of the third β-propeller domain, which is an essential region for the interaction with sclerostin." (PMID 35052419, 2021). "A point mutation in the SOST gene causes sclerosteosis, and a 52 kb deletion of the downstream gene of SOST causes van Buchem disease." (PMID 32733380, 2020). "Sclerostin deficiency results in excessive bone formation, as observed in sclerosteosis and van Buchem disease." (PMID 32733380, 2020). "The effect of sclerostin inhibition was further inferred from patients with life-long sclerostin deficiency, such as sclerosteosis or van Buchem disease, who exhibit increased bone mass." (PMID 33004873, 2020). "Sclerosteosis, which is mainly found in South Africa, is the result of a homozygous mutation in the SOST gene." (PMID 31858345, 2020).
sclerosteosis (continued). "Sclerosteosis and van Buchem disease are autosomal recessive skeletal dysplasia causing deficiency of sclerostin protein and progressive skeletal growth." (PMID 32733380, 2020). "SOST genetic mutation-induced high bone mass was reported in the 1950s, but the pathogenesis of the skeletal disease, named Sclerosteosis, was identified in 2001." (PMID 33363144, 2020). "Sclerostin deficiency in various rare genetic bone diseases, such as sclerosteosis and van Buchem disease, causes osteopetrosis, a high bone mass phenotype." (PMID 32733380, 2020). "Sclerosteosis arises from loss-of-function mutations within the SOST gene; whereas, van Buchem disease from deletion of a region (~52-kb) downstream of the SOST gene, which is relevant for proper gene expression." (PMID 33162933, 2020). "Genetic mutations affecting the SOST (chr17q12-21) gene lead to two similar syndromes: sclerosteosis and van Buchem disease, described in detail in previous reviews." (PMID 33162933, 2020). "Loss of sclerostin causes a high bone mass phenotype such as in sclerosteosis and Van Buchem’s disease." (PMID 32708317, 2020). "Considering the low or even unmeasurable serum levels of sclerostin in Van Buchem disease and sclerosteosis, the thought that high sclerostin levels lead to loss of bone mass and bone strength with an increased fracture risk is obvious." (PMID 31858345, 2020). "Sclerosteosis (OMIM: 269500) is a disease characterized by an increase in bone density owing to a loss-of-function mutation in the SOST gene encoding sclerostin." (PMID 31698687, 2019). "Conversely, inadequate WNT inhibition from mutations or deletions in the sclerostin-encoding SOST results in high bone mass phenotypes sclerosteosis (MIM 269500) and van Buchem disease (MIM 239100), respectively." (PMID 30858824, 2019). "The importance of SOST in bone formation is illustrated by sclerosteosis, a rare autosomal recessive disorder with a loss-of-function mutation in SOST (Sebastian & Loots, 2018;Yavropoulouet al., 2014)." (PMID 31031968, 2019). "Loss of the osteocyte-specific secreted Wnt antagonist sclerostin (Van Buchem disease or sclerosteosis) or mutations in the Wnt coreceptor LRP5, which prevent binding of the Wnt antagonists sclerostin and DKK1, have been shown to cause increased bone mass." (PMID 30770859, 2019). "Sclerostin has been described as a direct inhibitor of LPR5, since sclerostin inactivation leads to the same bone phenotype as activating mutations of LRP5 with enhanced bone growth known as sclerosteosis." (PMID 31752267, 2019). "SOST is a protein produced primarily by osteocytes and hypertrophic chondrocytes, and SOST mutation can lead to sclerosteosis and van Buchem disease." (PMID 28953627, 2017). "While sclerosteosis is caused by inactivating mutations of SOST, a 52 kb homozygous noncoding deletion 35 kb downstream of the SOST gene containing a regulatory element for SOST transcription is the cause of van Buchem disease." (PMID 27016922, 2016). "Sclerostin was discovered as a product of the SOST gene causing sclerosteosis, and van Buchem syndrome, and later confirmed in mice in which the SOST gene had been deleted or overexpressed." (PMID 26749312, 2016). "We identified one person with moderate HBM and a novel heterozygous nonsense SOST mutation predicted to prematurely truncate sclerostin, suggesting her to be a sclerosteosis carrier." (PMID 26348019, 2016). "The clinical manifestations reported in the studied brothers in the form of tall stature, distorted facies, orodental findings, syndactyly, and encroachment of cranial nerves are consistent with sclerosteosis and mutation in SOST gene." (PMID 25984533, 2015). "Five different loss-of-function mutations relevant to sclerosteosis in SOST gene have been reported as pathogenic in ClinVar database to date." (PMID 25984533, 2015). "According to ClinVar database, there are five SOST gene mutations that have pathogenic effect causing sclerosteosis." (PMID 25984533, 2015).